RNU6-347P (RNA, U6 small nuclear 347, pseudogene)
Gene: Small nuclear RNA gene on chromosome 20 (51,902,291 to 51,902,395, forward strand). Ensembl gene ENSG00000252467.
Homologues: Orthologues: chimpanzee U6 (99% identical), macaque U6 (88% identical), pig U6 (75% identical), mouse Gm23567 (71% identical), rat LOC120094409 (68% identical), dog U6 (66% identical), guinea pig U6 (62% identical). Paralogues in human: RNU6-17P (83% identical), RNU6-18P (83% identical), RNU6-33P (83% identical), RNU6-891P (83% identical), RNU6-1 (82% identical), RNU6-12P (82% identical), RNU6-13P (82% identical), RNU6-2 (82% identical), RNU6-22P (82% identical), RNU6-25P (82% identical), RNU6-29P (82% identical), RNU6-32P (82% identical), and 1287 more.